PRDX2 (peroxiredoxin 2)
Description:
Thiol-specific peroxidase that catalyzes the reduction of hydrogen peroxide and organic hydroperoxides to water and alcohols, respectively. Plays a role in cell protection against oxidative stress by detoxifying peroxides and as sensor of hydrogen peroxide-mediated signaling events. Might participate in the signaling cascades of growth factors and tumor necrosis factor-alpha by regulating the intracellular concentrations of H(2)O(2).
Synonyms: NKEF-B; TSA; NKEFB; TDPX1; PRP; PRXII; PRX2; MGC4104; HEL-S-2a; PTX1; TPX1
Tractability: PROTAC: ubiquitination databases record sites on it; its protein half-life has been measured.
Target class: Enzyme; Oxidoreductase
Gene: Protein-coding gene on chromosome 19 (12,796,817 to 12,801,849, reverse strand). Ensembl gene ENSG00000167815.
Subcellular location: Cytoplasm
Subcellular location (Human Protein Atlas): Cytosol
Pathways (Reactome):
Cellular responses to stimuli: Detoxification of Reactive Oxygen Species
Disease: Deregulated CDK5 triggers multiple neurodegenerative pathways in Alzheimer's disease models
Gene Ontology:
Molecular function: antioxidant activity; protein binding; thioredoxin peroxidase activity; thioredoxin-dependent peroxiredoxin activity; oxidoreductase activity; peroxiredoxin activity
Biological process: cellular response to oxidative stress; defense response to tumor cell; regulation of apoptotic process; removal of superoxide radicals; response to oxidative stress; hydrogen peroxide catabolic process; leukocyte activation; negative regulation of apoptotic process; positive regulation of blood coagulation
Cellular component: cytoplasm; cytosol; extracellular exosome
Genetic constraint (gnomAD): Loss-of-function variants: 10 observed, 19.87 expected, observed/expected ratio (o/e) 0.5, 90% interval 0.31 to 0.85. The upper end of that interval is the gene's LOEUF score, 0.85, which puts it in group 3 of 6, group 1 being the genes least tolerant of losing a copy. Missense variants: 226 observed, 272.09 expected, observed/expected ratio (o/e) 0.83, 90% interval 0.74 to 0.93. Synonymous variants: 118 observed, 114.88 expected, observed/expected ratio (o/e) 1.03, 90% interval 0.88 to 1.2.
Homologues: Orthologues: chimpanzee PRDX2 (100% identical), macaque PRDX2 (100% identical), dog PRDX2 (93% identical), guinea pig PRDX2 (92% identical), mouse Prdx2 (92% identical), rat Prdx2 (82% identical), tropical clawed frog prdx2 (74% identical), Drosophila melanogaster CG12896 (32% identical), Drosophila melanogaster Prx6b (32% identical), Drosophila melanogaster Prx6c (32% identical). Paralogues in human: PRDX1 (78% identical), PRDX4 (70% identical), PRDX3 (65% identical), PRDX6 (32% identical).
Diseases named in the same sentence as PRDX2 in open-access papers:
PRDX2 is named in the same sentence as 196 diseases in open-access papers, as found by Europe PMC text mining. Sharing a sentence is not in itself a finding about the gene and the disease. The quoted sentences say what the papers report.
colorectal cancer (40 papers, 2016 to 2025). A primary or metastatic malignant neoplasm that affects the colon or rectum. "Previous studies have shown that PRDX2 expression is associated with the development of different solid cancers, including colorectal cancer, lung adenocarcinoma, cervical cancer, ovarian cancer, and gastric cancer." (PMID 40932790, 2025). "As a result of excessive levels of oxidative molecules, a knockdown of peroxiredoxin-2 reduced VEGFR-2 activation in colorectal cancer and caused VM formation." (PMID 38178861, 2023). "PRDX2 was associated with prognosis in multiple cancers, such as colorectal cancer, hepatocellular carcinoma and esophageal squamous cell carcinoma." (PMID 35350568, 2022). "In colorectal cancer, increased expression of Prdx2 was found to be significantly associated with advanced local invasion, increased lymph node metastasis, and shorter disease-free survival." (PMID 32929349, 2020). "It has been identified that PRDX2 is overexpressed in various type of cancers including colorectal cancer and cervical cancer and associated with the tumor metastasis and prognosis of patients." (PMID 32337219, 2020). "Furthermore, overexpression of PRDX2 was associated with colorectal cancer progression and shorter patient survival." (PMID 30104402, 2018). "In addition, PRDX2 is a diagnostic marker in squamous cervical cancer, a predictive indicator for the induction chemotherapy response in osteosarcoma, and a prognostic biomarker in ovarian cancer and colorectal cancer." (PMID 33819194, 2021). "MS-CETSA was also used to reveal that ainsliadimer A targets PRDX1 and PRDX2, which induces reactive oxygen species (ROS)-mediated apoptosis in colorectal cancer cells." (PMID 40362180, 2025). "Studies have demonstrated that downregulation of PRDX2 inhibits tumor cell proliferation, migration, and invasion in gastric cancer and colorectal cancer." (PMID 40281661, 2025). "They concluded that AIN induces oxidative stress and mitochondrial dysfunction by inhibiting PRDX1 and PRDX2, which results in ROS-mediated apoptosis in colorectal cancer cells." (PMID 40362180, 2025). "The results provided direct biochemical evidence that AIN increases the thermal stability of PRDX1 and PRDX2 in intact colorectal cancer cells, which confirmed their role as cellular targets." (PMID 40362180, 2025). "PRDX2 expression is elevated in several human solid tumors such as lung adenocarcinoma, gastric cancer, and colorectal cancer." (PMID 40645965, 2025). "Several compounds or small molecule drugs have been found to inhibit the proliferation and induce apoptosis in gastric and colorectal cancer cells by directly targeting PRDX2 and inhibiting its peroxidase activity." (PMID 39234629, 2024). "Ainsliadimer A, a sesquiterpene lactone dimer with antitumor activity, inhibits PRDX2 and shows an antitumor effect in colorectal cancer cells." (PMID 38731835, 2024). "Other studies have revealed that PRDX2 gene knockout inhibits the growth of colorectal cancer cells, potentially mediated by the p38/FOXO pathway, which regulates cell cycle and autophagy, thus indicating a role for PRDX2 in promoting cell proliferation." (PMID 37758743, 2023). "PRDX2 facilitates the proliferation of colorectal cancer cells and non-small cell lung cancer cells." (PMID 35350568, 2022). "Previous studies detected high PRDX2 levels in various types of malignant epithelial tumors including colorectal cancer, and PRDX2 was shown to promote tumor formation by regulating various cancer-related cellular signaling pathways." (PMID 33819194, 2021). "PRDX2 is also targeted by miR-200b, which suppress growth, invasion and metastasis in colorectal cancer and is connected to enhanced chemotherapeutic resistance through disruption of the c-Myc/miR-200b-3p/PRDX2 regulatory loop." (PMID 34199590, 2021). "To determine the mRNA expression of PRDX2 in colorectal cancer, we downloaded the GSE113513 and GSE10950 datasets deposited in the GEO database." (PMID 34117220, 2021).
colorectal cancer (continued). "PRDX2 knockdown inhibited cancer cell growth, colony formation, and xenograft tumorigenesis derived from human colorectal cancer cells." (PMID 34117220, 2021). "our previous study also demonstrated that PRDX2 knockdown inhibited the growth of colorectal cancer cells in part by downregulating Wnt/β-catenin signaling." (PMID 33819194, 2021). "Our previous study showed that PRDX2 is closely correlated with poor differentiation, advanced stage, lymph node metastasis of colorectal cancer." (PMID 34117220, 2021). "Here, the results indicated that PRDX2 expression was upregulated in colorectal cancer and closely correlated with poor prognosis." (PMID 34117220, 2021). "In summary, we found that PRDX2 is highly expressed in colorectal cancer tissues and can promote colorectal cancer cell proliferation." (PMID 34117220, 2021). "PRDX2 is a member of the peroxiredoxins (PRDXs) family that has been reported to have a high level of expression in many cancers, such as colorectal cancer, gastric cancer, and lung cancer." (PMID 34117220, 2021). "PRDX2 is a member of the peroxiredoxin family reported to have a high level of expression in colorectal cancer." (PMID 34117220, 2021). "PRDX2 is a multi-functional gene in colorectal cancer and has potential to be a therapeutic target in CRC treatment." (PMID 32692719, 2020). "Overexpression of PRDX2 is a potential biomarker for colorectal cancer, OSCC, osteosarcoma and ovarian cancer." (PMID 33332365, 2020). "A recent study reported that miR-200b-3p is a direct posttranscriptional regulator of PRDX2, which suppresses the malignant behaviors of colorectal cancer (CRC) cells through inhibition of PRDX2." (PMID 32908916, 2020). "In a previous study 36, PRDX2 was shown to be elevated in colorectal cancer tissues compared to the normal controls." (PMID 32231717, 2020). "For example, it has been indicated that PRDX2 is upregulated in colorectal cancer and exerts a tumor promoting role in the progression of colorectal cancer." (PMID 32337219, 2020). "In colorectal cancer, as the most abundant isoform of the PRDXs in the tumor tissues 75, PRDX2 was reported to be a tumor-promoter in colorectal cancers with APC mutation." (PMID 32231717, 2020). "Colorectal cancer (CRC) is a prevalent worldwide disease in which the antioxidant enzyme peroxiredoxin 2 (PRDX2) plays an important role." (PMID 32692719, 2020). "For example, Prdx2 knockdown inhibited colorectal cancer cell growth, which had high Prdx2 mRNA expression." (PMID 30988280, 2019). "The tumor promoting effect of PRDX2 was demonstrated in colorectal carcinoma through up-regulation of Wnt/β-catenin pathway, and prostate cancer through increased activation of the androgen receptor (AR) signaling pathway." (PMID 30104402, 2018). "Our most recent studies show that PRDX2 promotes vasculogenic mimicry formation by activating VEGFR2 and contributes to maintain colorectal cancer stem cell-like properties, suggesting a possible implication of PRDX2 in regulating CRC invasion and metastasis." (PMID 29258530, 2017). "In the GENT database, PRDX2 is up-regulated in colorectal cancers compared with corresponding normal tissues." (PMID 28125800, 2017). "We found that all colorectal cancer cell lines revealed higher PRDX2 mRNA expression compared with those in HCEC." (PMID 28125800, 2017). "Functional studies demonstrated that PRDX2 play a tumor promoting effect in various cancers including colorectal carcinoma." (PMID 28125800, 2017). "PRDX2 also regulates neointima formation in colorectal cancer through the activation of VEGFR2." (PMID 39234629, 2024). "Additionally, in our study, we conducted validation of the impact of PRDX2 on VM formation in ccRCC, which is similar to its effect in colorectal cancer, demonstrating a promotion effect." (PMID 38178861, 2023).
colorectal cancer (continued). "Although the relationship between PRDX2 and prognosis of HCC patients has not been reported, the low expression of PRDX2 was confirmed to be associated with liver metastasis and poor overall survival rate of colorectal cancer." (PMID 33771165, 2021). "Our findings provide novel insights into the role of PRDX2 in promoting colorectal cancer development and suggest that PRDX2 could be a promising target for colorectal cancer treatment." (PMID 34117220, 2021). "However, the mechanisms by which PRDX2 promotes the proliferation of colorectal cancer are still unclear." (PMID 34117220, 2021). "Functionally, PRDX2 promoted the proliferation of colorectal cancer cells." (PMID 34117220, 2021). "PRDX2 promoted tumor angiogenesis via activating VEGFR2 in colorectal cancer." (PMID 32908916, 2020). "In addition, Prdx2 inhibited EMT in a colorectal cancer model, reducing invasive characteristics, via Twist1, Snail, ZEB1, and ZEB2." (PMID 33182509, 2020). "Considering the important roles of PRDX2 in resistance of human colorectal cancer cells to chemotherapy and radiotherapy 77, 78, it might be a new target for COAD therapy." (PMID 32231717, 2020). "Knockdown of PRDX2 could inhibit the growth and promote apoptosis of colorectal cancer cells and increase the sensitivity of colon cancer cells to 5-FU." (PMID 32337219, 2020). "Consistently, PRDX2 functions as a tumor promoter in colorectal cancer." (PMID 33332365, 2020). "Deleting PRDX2 or blocking the function of PRDX2 in colorectal cancer may yield efficacious results." (PMID 32692719, 2020). "Furthermore, silencing of Prdx2 enhances the response of colorectal cancer cells to ionizing radiation and oxaliplatin." (PMID 33182509, 2020). "In addition, the overexpression of peroxiredoxin-2 induces Akt activation in human colorectal cancer tissues." (PMID 31769426, 2019). "Thus, we aimed to identify and confirm the expression of PRDX2 in CRC by several lines of evidence, and further investigate the prognostic value of PRDX2 in CRC using a large number of colorectal cancer tissue samples." (PMID 28125800, 2017). "In addition, down-regulation PRDX2 expression inhibited VEGF mimicry formation of HCT116 cells through targeting VEGFR2 activation in colorectal carcinoma." (PMID 28125800, 2017). "The results suggest that Prdx2 may be an effective therapeutic target for the elimination of CSCs in colorectal cancer." (PMID 27894099, 2016). "For instance, PRDX2 silencing has been shown to inhibit proliferation and invasion in non-small cell lung cancer cells, promote growth, survival, and resistance to cisplatin in gastric cancer cells and impair proliferation, cell cycle, and autophagy in colorectal cancer cells." (PMID 38188679, 2023). "Strategies targeting PRDX2 may be developed as therapies for colorectal cancer." (PMID 34117220, 2021). "What’s more, PRDX2, as a target of miR-200b-3p, promoted the proliferation, invasion and EMT of colorectal cancer cells; PRDX3, as a target molecule of miR-383, regulated the growth of medulloblastoma cells." (PMID 33771165, 2021). "In a previous study, we provided evidence that PRDX2 expression serves as an independent and unfavorable prognostic indicator for stage I-III colorectal cancer patients." (PMID 33819194, 2021). "The up-regulation of both PRDX2 and PRDX6 is described in many tumors and correlated with invasiveness, migration, drug resistance and enhancing stem cell properties, in particular in NSCLC, colorectal cancer, and esophageal carcinoma." (PMID 34320944, 2021). "Our results showed that PRDX2 is not only highly expressed in CRC but also in other cancers, suggesting that our studies in colorectal cancer could provide a reference for other cancers." (PMID 32692719, 2020).
colorectal cancer (continued). "The protein and mRNA levels of PRDX2 were found to be significantly over-expressed in all six examined human primary colorectal cancer samples compared with adjacent noncancerous tissues." (PMID 28125800, 2017). "The present study was to investigate the clinical significance of peroxiredoxin 2 (PRDX2), an oncoenzyme, in the development and progression of colorectal cancer(CRC).We found levels of PRDX2 mRNA and protein were higher in CRC cell lines than in normal human colonic epithelial cells." (PMID 28125800, 2017). "Furthermore, peroxiredoxin 2 (PRDX2), a major antioxidant enzyme, stimulates VM channel formation in colorectal cancer by keeping VEGFR-2 in its activated state." (PMID 29112161, 2017).
breast carcinoma (23 papers, 2007 to 2025). "In this regard, the reduced expression of peroxiredoxin 2 among the differentially-expressed proteins in the ZR-75-1 cell line implies the high risk of relapse and metastasis for the luminal B subtype of breast cancer." (PMID 32846884, 2020). "Similarly, PRDX2 knockdown sensitizes the lung metastatic variant of MDA-MB-435 breast cancer cells to oxidative stress and sensitizes MCF-7 breast cancer cells to DOX-induced apoptosis and ionizing radiation-induced cytotoxicity." (PMID 40214422, 2025). "Among the PRDX isoforms, PRDX1 and PRDX2 have been identified in EVs associated with breast cancer." (PMID 40214422, 2025). "More recently, the presence of full-length recombinant proteins—alpha 1-antitrypsin (A1AT), triose-phosphate isomerase 1 (TPI1), peptidyl-prolyl cis-trans isomerase A (PPIA), and peroxiredoxin 2 (PRDX2)—as microarrays evaluated potential antigens associated with early-stage breast cancer tumors." (PMID 37887534, 2023). "Moreover, the expression of PRDX‐2 in breast cancer cells is linked to a glucose‐dependent phenotype, which is different from bone metastatic cells." (PMID 32232956, 2020). "Importantly, PRDX2 has a direct role in lung metastasis, and high expression of PRDX2 in breast cancer is associated with progression to lung metastasis." (PMID 33332365, 2020). "Liu and colleagues reported that in a MDR (multidrug resistant) cell line MCF7/AdVp3000 the expression of PRDX6 was increased and the expression of PRDX2 was decreased, which suggested they might cause drug resistance to chemotherapy in breast cancer." (PMID 17980029, 2007). "PRDX2 was reported to promote tumor growth in different solid cancers, including colorectal, non–small cell lung, ovarian, and breast cancers." (PMID 40932790, 2025). "Immune‐related proteins osteopontin, lactotransferrin, calreticulin, and peroxiredoxin 2 were selected as potential biomarkers of MDSC‐producing breast cancer." (PMID 39939411, 2025). "Overall, these studies suggest that PRDX1 and PRDX2 promote breast cancer cell survival via induction of radio/chemoresistance and inhibition of oxidative stress-induced cell death." (PMID 40214422, 2025). "Of these proteins, previous studies have shown that high expression of glyceraldehyde-3-phosphate dehydrogenase, peroxiredoxin-2 and histone H2A type 2-A in breast cancer tissues are inversely correlated with overall survival and tumour aggressiveness." (PMID 34832109, 2021). "Peroxiredoxin-2 can promote breast cancer metastasis to the lung by regulating oxidative stress, and silencing peroxiredoxin-2 can inhibit breast cancer lung metastasis by inducing oxidative damage." (PMID 33926551, 2021). "PRDX2, has been reported to specifically regulate the oxidative and metabolic stress response of metastatic breast cancer cells in lungs." (PMID 31402980, 2019). "We seek to validate the dependence of mammary tumour cell survival on an increased expression of PRDX1 or PRDX2 within the current study." (PMID 30287919, 2018). "Three of the five individual TAAs, FKBP52, PPIA, and PRDX2, showed significantly increased reactivity in breast carcinoma patients and breast carcinoma in situ patients compared to healthy controls." (PMID 21423545, 2011). "Furthermore, a study focused in breast cancer implied secretion of PRDX2 where tumor interstitial fluid (TIF) and normal interstitial fluid (NIF) from prospective cancer patients were compared, employing proteomic and immunohistochemistry analysis." (PMID 28261610, 2017). "Furthermore, inhibiting PRDX2 expression decreased the growth of breast cancer metastatic cells in lungs." (PMID 28125800, 2017). "In addition, the overexpression of PRDX2, resulting in increased resistance of breast cancer cells to ionizing radiation, and involvement of PRDX in breast cancer resistance to docetaxel therapy were also observed." (PMID 17980029, 2007). "Also, PRDX 1 and PRDX2 are highly expressed in breast cancer." (PMID 40214422, 2025).